MTOR (mechanistic target of rapamycin kinase)
Diseases named in the same sentence as MTOR in open-access papers (continued):
Sharing a sentence is not in itself a finding about the gene and the disease.
cancer (continued). "Owing to its activation in cancer cells, specific inhibitors of MTOR including rapamycin have been considered as attractive reagents for cancer therapy." (PMID 35159256, 2022). "Activated by AKT, the mTOR pathway can represent an effective target to treat various types of cancer." (PMID 36077338, 2022). "Lactate dehydrogenase (LDH), which is commonly activated by oncoproteins like cMyc, HIF-1α, and mTOR in cancer cells, converts pyruvate to lactate while simultaneously oxidizing NADH to NAD+." (PMID 36419156, 2022). "Again, these results are reasonable in terms of the significant negative correlations between DEPTH2 scores and the enrichment scores of the MAPK, PI3K-Akt, and mTOR signaling pathways in cancer cell lines (P < 0.05)." (PMID 35365157, 2022). "The immunohistochemistry (IHC), immunofluorescence, Western blot, and RT-qPCR assays have confirmed that mTOR is upregulated while miR-99b-5p is downregulated in different patient cohorts and a panel of cancer cell lines." (PMID 36077039, 2022). "TBMS-1 selectively binds mTOR kinase and suppresses mTORC1 activation to dysregulate PD-1/PD-L1 interactions and improve T cell cytotoxicity towards cancer cells by suppressing PD-L1." (PMID 35910383, 2022). "The profound knowledge of mTOR signaling will be indispensable for the development of novel therapies of cancer and metabolic diseases." (PMID 35740927, 2022). "Since the PI3K/mTOR signalling pathway is recognized as being crucial for therapeutic interventions in many cancers, including EOC, an understanding of the molecular mechanisms that regulate PI3K/mTOR signalling is required." (PMID 36114703, 2022). "Then, PI3P recruits and activates AKT, a kinase that regulates various downstream pathways sustaining cancer cells metabolism, especially the mammalian target of rapamycin (mTOR), sustaining protein translation, cell cycle progression, survival, and EMT." (PMID 35626081, 2022). "The involvement of mTOR in the regulation of PD-L1 expression has been controversial among different types of cancer." (PMID 36009440, 2022). "They revealed that this compound induces autophagy via JNK activation and mTOR inhibition that increases the resistance of cancer cells to apoptosis." (PMID 36428613, 2022). "As an effective pharmacological compound for cancer, LA induces apoptosis in different cancers via multiple pathways, including P13-Akt-mTOR, VEGFR2, c-Met, PLCγ1, MAPT, JNK/p38, and ERK1/2, along with a combination of regulatory targets." (PMID 35677438, 2022). "mTOR inhibitors, such as rapamycin and everolimus, similarly work to kill cancer cells as mTOR plays a pivotal role in governing cell growth and proliferation." (PMID 36505146, 2022). "The drug-resistant gene, NPRL2, showed increased expression in cancer cells and upon upregulation, it repressed the mTOR signaling pathway to activate the process of autophagy and suppressed apoptosis." (PMID 36365094, 2022). "To examine the relevance of the persister phenotype in clinical cancer treatments, we derived an mTOR-regulated persister (MP) signature by identifying the common transcriptomic changes in the Torin1-treated vs control and persister vs control comparisons." (PMID 36396656, 2022). "The inhibition of the PI3K/AKT/mTOR pathway represents an attractive target for cancer treatments, and massive potential targeted drugs are in preclinical development or early clinical trials." (PMID 36349192, 2022). "During tumor development, myriad oncogenic pathways such as DVL3/Wnt/β-catenin, AKT/ERK/FOXM1, and mTOR/p70S6K signals etc. are constitutively activated in cancer cells." (PMID 35743298, 2022).
cancer (continued). "The PI3K/AKT/mTOR pathway is commonly hyperactivated in many types of cancer and correlates with poor clinical prognosis." (PMID 36189258, 2022). "Because rapamycin has a limited ability to regulate all actions of mTORC1, and thus its application in cancer treatment, a great deal of research has gone into developing compounds that can block the catalytic activity of mTOR." (PMID 36109789, 2022). "Pharmacological suppression of mTOR activity in cancer cells from diverse tissue origins leads to the persistence of a reversibly resistant population, which is otherwise eliminated by chemotherapeutic agents." (PMID 36396656, 2022). "The mammalian target of rapamycin (mTOR) signaling pathway is a route for targeting cancers that plays a versatile role in autophagy, cell proliferation, and apoptosis." (PMID 35795855, 2022). "Past studies have suggested that KRT17 mediates cancer progression through the AKT/mTOR or Wnt/β-catenin axis." (PMID 36248412, 2022). "The relationship between HSF1 and mTOR, also seen in other cancer types, was demonstrated as a necessary component for MYC-driven HCC." (PMID 35311075, 2022). "Recently, IL6/PI3K signaling was described as an activator of disseminated tumor cells (DTCs) and initial perivascular growing cancer cells are sensitive to dual PI3K/mTOR inhibition during brain colonization." (PMID 36224342, 2022). "KEGG pathway analysis results showed that 10 significant pathways (P < 0.05) were enriched, and most of them were cancer-related, such as mammalian target of rapamycin (mTOR) signaling pathway, Ras signaling pathway, and Pathways in cancer." (PMID 36033494, 2022). "TEM is an FDA-approved targeted anti-cancer drug that limits the survival of cancer cells and promotes autophagy by inhibiting phosphorylation of mTOR in cancer cells." (PMID 36077620, 2022). "In conclusion, the levels of phosphorylated AKT, mTOR, and p70s6K were significantly decreased in hinokitiol-treated cancer cells." (PMID 35399709, 2022). "mTOR signaling regulates various biological processes such as cell metabolism, immunity, growth, and autophagy, and its dysfunction plays an important role in a variety of cancers; thus, mTOR is considered as one of the potential targets for tumor therapy." (PMID 36139062, 2022). "Studies have shown that the PI3K/AKT/mTOR signaling pathway is a main cancer-promoting factor and participates in a variety of physiological functions and disease processes such as cell survival, angiogenesis, proliferation, and metabolism." (PMID 35281608, 2022). "In agreement, loss of miR-204 results in BDNF/TRKB overexpression and activation of the Akt/mTOR/Rac1 signalling pathway, cancer cell migration and invasion in many cancers." (PMID 35158801, 2022). "NVP-BEZ235 is a dual PI3K/mTOR inhibitor in phase II clinical trials in advanced cancer patients to study its pharmacokinetics and pharmacodynamics." (PMID 35165269, 2022). "IGF-1R activates mTOR, promoting protein and lipid biosynthesis, leading to accelerated glycolysis and macromolecule construction, which are important for uncontrolled cancer cell proliferation." (PMID 35890085, 2022). "By mTOR mediation, Arg thus has profound impacts on protein synthesis, lipid synthesis and nucleotide synthesis of cancer cells." (PMID 35469201, 2022). "Phosphoinositide 3-kinase (PI3K)/mammalian target of rapamycin (mTOR) pathway components are key therapeutic targets in cancer, immunity, and thrombosis." (PMID 35626227, 2022). "AMPK and its downstream mTOR are involved in the regulation of the material and energy metabolism of cancer cells 30,903,363." (PMID 35953532, 2022).
cancer (continued). "Over the past decades, the role of mTOR signaling in aging, metabolism and cancer has been extensively studied." (PMID 35938153, 2022). "Yet, a significant amount of energy has been expended on successfully “drugging” this kinase for cancer treatment and mTOR’s relevance in cancer pathogenicity is rarely in question." (PMID 36551828, 2022). "Evidence has shown that mTOR‐related mechanisms contribute to malignant phenotypes in multiple cancers." (PMID 35322916, 2022). "We illustrate the utility of iLINCS with three use cases involving analysis of cancer proteogenomic signatures, COVID 19 transcriptomic signatures and mTOR signaling." (PMID 35945222, 2022). "In the vast pool of regulators, a few unique players function through all three to control cancer development, such as cell proliferation factor mammalian target of rapamycin (mTOR) and oncogene c-Myc." (PMID 35155432, 2022). "These combinations offer achieving higher radio- and chemo- sensitization through alteration in the key signaling pathways such as AMPK, STAT3, NF-ĸB, Hedgehog, PI3K/Akt/mTOR, Notch, GSK3β, and Wnt related to cancer stemness and drug resistance." (PMID 35740529, 2022). "Developing a better mechanistic understanding of cancer cell responses to mTOR inhibitors will help design improved treatment schemes to drive more durable responses to these promising therapies." (PMID 35484114, 2022). "Everolimus is an oral inhibitor of the mTOR pathway that shows great promise in several types of cancers, in vitro and in vivo." (PMID 36077529, 2022). "The mTOR pathway is involved in many hallmarks of cancer, including cell growth, metabolic reprogramming, proliferation, and inhibition of apoptosis, and is upregulated in HCC tissue samples." (PMID 36344496, 2022). "Similar to the miR-99b-5p effect on mTOR expression/location, the AR expression levels were significantly reduced in miR-99b-5p mimic vs. NS transfected cancer cells (total lysates)." (PMID 36077039, 2022). "As reported, MTOR signaling pathway was frequently activated to regulate cancer cell growth and metabolism." (PMID 35572505, 2022). "It is well known that PI3K-Akt-mTOR signaling pathway plays an important role in various type of cancer cells." (PMID 36439106, 2022). "Research has shown that the PI3K/AKT/mTOR pathway plays an important role in the process by which cancer becomes resistant to chemotherapy, as well as cancer cell growth, survival and blood supply." (PMID 35382842, 2022). "Since the development of drugs targeting mTOR, there is proven efficacy in terms of survival benefit in cancer and allograft rejection." (PMID 35845058, 2022). "The PI3K/Akt/mTOR signaling pathway is important not only in the development of cancer but also in the proliferation, adhesion, migration, metabolism, and survival of normal cells." (PMID 36496564, 2022). "The activation of the PI3K/Akt/mTOR pathway is important to cancer cell growth and its therapeutic resistance." (PMID 36226253, 2022). "In vitro, the inhibitory effect of samotolisib on PI3K/Akt/mTOR signalling leads to G1 cell cycle arrest and produces extensive antiproliferative activity in cancer cell screening." (PMID 35614940, 2022). "All these demonstrate that mTOR plays a central role in the occurrence and progression of a variety of cancers." (PMID 35740927, 2022). "This section, reported in detail the bioactive compounds that have been studied for their important activity on the PI3K-Akt-mTOR pathway in cancer." (PMID 36428613, 2022).
cancer (continued). "When we investigated the cytotoxic effect of anti-cancer drug (mTOR inhibitor, RSV) in SIRT3 OE cancer cell, it showed the number of cancer cell was significantly decreased in a dose-dependent manner." (PMID 35671305, 2022). "Mammalian target of rapamycin (mTOR) kinase, mTORC1, and mTORC2 complexes are considered critical drivers of cancer drug resistance that integrate signaling pathways driving cell metabolism and growth." (PMID 36499000, 2022). "It is important to distinguish the normal metabolic stimulation of mTOR in muscle cells from what occurs in cancer cells." (PMID 35301826, 2022). "The direct effect of metformin is an activation of AMPK leading to the mammalian target of rapamycin (mTOR) signaling inhibition, which, in turn, plays a role in the proliferation of cancer stem cells." (PMID 35745575, 2022). "By the same token, metformin regulates PDAC carcinogenesis not only through mTOR activation but also via AMPK-mediated and AMPK-independent mechanisms by up-regulating the expression of REDD1 to cause cancer cell cycle arrest." (PMID 35454306, 2022). "Since the PI3K/AKT/mTOR pathway is involved in the mechanism of autophagy, targeted modulation of this pathway has become an important approach for cancer therapy." (PMID 36561529, 2022). "The mammalian target of rapamycin (mTOR) has emerged as a critical effector in cell signaling pathways commonly dysregulated in human cancers, and is well-known involved in the regulation of cell cycle." (PMID 35091546, 2022). "The top 30 significantly enriched KEGG pathways mainly included cell cycle, MAPK, VEGF, NOTCH, and mTOR signaling pathways, whose activation or inactivation is closely correlated with cell survival, proliferation and the progression of cancer." (PMID 36119057, 2022). "It has been established that the activation of mTOR inhibits autophagy, and the inhibition of mTOR induces autophagy in cancer cells." (PMID 35408483, 2022). "Myrtucommulone A was found to alter PANC-1 cell morphology, inhibit cell migration, and downregulate the PI3K/Akt/mTOR and autophagy signaling pathways in nutrient-deprived media, leading to cancer cell death." (PMID 36235333, 2022). "The PI3K/AKT/mTOR pathway is common in cancers and plays a key role in regulating the tumor microenvironment." (PMID 36284313, 2022). "We demonstrated that FGFR-TKI treatment response/resistance in cancer cells visualized by 18F-FDG PET imaging was correlated with FGF/FGFR signaling-mediated glucose metabolism via mTOR/HK2." (PMID 36168616, 2022). "Another study suggested that m6A RNA modification catalyzed by enzymes including ALKBH5 and FTO had a fundamental role in the regulation of PI3K/Akt/mTOR signaling pathway in cancer." (PMID 35371987, 2022). "YAP is also overexpressed in human lung adenocarcinoma tissues, regulates autophagy and proliferation in A549 and H1299 cancer cells, and induces activation of Akt/mTOR signaling through suppression of PTEN via the Hippo pathway." (PMID 35163745, 2022). "The mutated genes at genome level were significantly enriched in functions or signaling pathways for cancer development, such as epidermal development, cell migration, Wnt signaling, ErbB signaling, and mTOR signaling." (PMID 35186034, 2022). "On the contrary, mRNA translation and mTOR pathways are often up-regulated in some abnormal proliferative diseases, including malignant tumors." (PMID 35740927, 2022). "This suggests a greater role for translational alterations in gene expression and metabolism in mTOR-dysregulated cancer than previously thought." (PMID 36097292, 2022). "Over the last decade, many discoveries have shown that the mTOR pathway is activated in a wide variety of cellular processes and is deregulated in human diseases such as cancer." (PMID 35444553, 2022). "In general, the cancer cell proliferation, motility, survival and apoptosis associated with PI3K/Akt/mTOR and MAPK signaling pathways have been well documented." (PMID 36506551, 2022).
cancer (continued). "The kinase mTOR functions as a master regulator of the PI3K‐Akt–mTOR pathway which is considered the most deregulated signaling pathway in cancer." (PMID 35587712, 2022). "Among the signaling pathways, PI3K/AKT/mTOR/GSK-3β is the classical metabolism pathway involved in cancer cell growth." (PMID 35392088, 2022). "Numerous studies have been conducted to evaluate the effect of combining mTOR inhibitors with other immunotherapies in different types of cancer." (PMID 36428613, 2022). "Of note, Torin-1-mediated cancer stemness up-regulation was significantly reduced when cells were treated with HCQ, suggesting that autophagy plays a crucial role in mTOR-mediated cancer stemness repression." (PMID 35406578, 2022). "This transporter has been shown to be upregulated in several cancers and to be involved in cell growth, proliferation, and the mechanistic target of rapamycin kinase (mTOR) pathway in breast, pancreatic, and colonic cancer cell lines." (PMID 35372502, 2022). "Similar to the effects of miR-99b-5p in PCa cells, all the six cancer cell lines showed a generalized reduction in mTOR (green fluorescence) and pmTOR (red fluorescence) levels in miR-99b-5p transfected vs. NS transfected cells." (PMID 36077039, 2022). "LHPP deregulated AKT and mTOR phosphorylation to repress cell proliferation and progression in colorectal, cervical, bladder and thyroid cancers." (PMID 36376886, 2022). "It has been found that the phosphatidylinositol-3-kinase (PI3K)/protein kinase B (AKT)/mammalian target of rapamycin (mTOR) signaling pathway is overstimulated in cancer cells that are resistant to chemotherapy, radiation, and hormone therapy." (PMID 36555391, 2022). "The dysregulation of the Wnt/β–catenin signaling pathway along with other targets including mTOR leads to certain cancers including pancreatic ductal adenocarcinoma." (PMID 35795855, 2022). "mTOR inhibition elevated lysosomal catabolism of extracellular proteins and promoted cancer cell survival under nutrient-depleted conditions." (PMID 36046825, 2022). "In particular, in cancer cells mTOR inhibition due to nutrient depletion promotes the tensin-dependent maturation of sub-nuclear fibrillar adhesions and the ensuing localized endocytosis of fibronectin-bound active α5β1 integrin." (PMID 35545719, 2022). "We explored the role of hub genes in well-known cancer-related pathways including TSC/mTOR, RTK, RAS/MAPK, PI3K/AKT, hormone ER, hormone AR, EMT, DNA damage response, cell cycle, and apoptosis pathway." (PMID 35957696, 2022). "The mTOR, in regulating many facets of cancer, including cell cycle, survival, metabolism, motility, and genomic instability, has been found in numerous studies, and mTOR signaling is generally aberrantly active in many malignancies." (PMID 36428613, 2022). "The mTor pathway is responsible for poor prognosis due to the aggressive nature of the cancer and its good tissue invasion property." (PMID 35145999, 2022). "The PI3K/AKT/mTOR pathway has been proven that it is aberrantly hyperactivated in many types of cancer that has a strong relationship with poor clinical prognosis." (PMID 36189258, 2022). "Except for pathways in apoptosis and transcriptional dysregulation in cancer, the top 8 signaling pathways annotated with a significant number of DEGs were: mTOR, Hippo, FoxO, CSC, Wnt, MAPK, apoptosis, and Hedgehog signaling pathways." (PMID 35359411, 2022). "Apoptosis-suppressing gene MTOR which co-appears with "Endometrial" 63 times, with "Cancer" 1896 times, ranked 19th in DriverRWH, but ranked 112th, 182th, and 1380th in Dawnrank, MutsigCV and OncodriveFML." (PMID 35831792, 2022).